TLR4 (toll like receptor 4)
Diseases named in the same sentence as TLR4 in open-access papers (continued):
Sharing a sentence is not in itself a finding about the gene and the disease.
Pain (10 papers, 2014 to 2024). An unpleasant sensory and emotional experience associated with actual or potential tissue damage, or described in terms of such damage. "In contrast, G2A seems to contribute to oxaliplatin-induced mechanical hypersensitivity via interaction with the TRPV1 channel in sensory neurons and mediates macrophage migration by activation of the Toll-like receptor 4 (TLR4) pathway in early nerve-injury-induced neuropathic pain." (PMID 34440817, 2021). "HMGB1 neuronal signalling in neuropathic pain may be dependent on either of two receptors for TLR4 and/or advanced glycation end products (RAGE)." (PMID 25120576, 2014). "The link between TLR4 and TRPV1 in pain conditions, including paclitaxel-induced peripheral neuropathic pain, has been well documented." (PMID 31775332, 2019). "More studies are required to confirm whether Tan IIA produces protective effects to alleviate hyperpathia in SNL-induced neuropathic pain, and whether Tan IIA downregulates HMGB1 and TLR4 expression in the spinal cord is not yet clear." (PMID 25120576, 2014).
pancreatic adenocarcinoma (10 papers, 2015 to 2025). "A similar prediction of worse outcome was also reported for TLR-4 in patients with pancreatic adenocarcinoma, where its higher expression was significantly associated with a shorter OS." (PMID 33008143, 2020). "Previously, we have described a technically similar engineered pancreatic adenocarcinoma cell line (opto-TLR4 PANC-1) that allows time- and voltage-dependent TLR4 activation by blue light, which can be switched off again in the dark." (PMID 36899833, 2023). "Our study provides new evidence that ferrichrome influences antitumor immune response in pancreatic adenocarcinoma by abrogation of M2-like polarization of TAMs while promoting M1-like polarization via activation of TLR4 signaling." (PMID 36333531, 2022). "Augmented Toll-like receptor 4 (TLR4) expression was found in nearly 70% of patients with pancreatic adenocarcinoma, which is correlated with increased tumorigenesis and progression." (PMID 34502140, 2021). "Lipopolysaccharide (LPS) can bind to the Toll-like (TLR) receptors; TLR2, TLR4, and TLR9 are associated with pancreatic adenocarcinoma development." (PMID 32344895, 2020). "In addition, TLR2, TLR4, and TLR9 and the downstream target of TLR4, MyD88, are associated with pancreatic adenocarcinoma development." (PMID 32344895, 2020). "Additionally, we examined the expression levels of TLR4 between normal pancreatic tissues and pancreatic adenocarcinoma (PAAD) tissues at both the transcriptional and translational levels." (PMID 40696496, 2025). "In pancreatic adenocarcinoma (PDAC), tumorigenesis is promoted by suppression of the function of DCs by exosomes carrying miR-203, which downregulates Toll-like receptor 4 (TLR4), tumor necrosis factor-α (TNF-α), and IL-12 expression, and ultimately prevents antigen presentation by DCs." (PMID 33586060, 2021).
pyelonephritis (10 papers, 2009 to 2026). An inflammatory process affecting the kidney. "In the pediatric population, the TLR4-Asp299Gly polymorphism has been detected more frequently in patients with pyelonephritis, is more common in girls, and is always associated with E. coli." (PMID 41598258, 2026). "Ammonium chloride acidosis (NH4Cl‐A) markedly impairs UPEC clearance and exacerbates pyelonephritis in innate immune competent (Tlr4‐sufficent) mice prone to vesicoureteral reflux." (PMID 36151614, 2022). "During kidney infection, IFNγ stimulation has been shown to increase TLR4 and TLR2 expression in infected kidneys." (PMID 34015044, 2021). "Zishenwan protected rats from pyelonephritis which related to the increase of SIgA, the regulation of interleukins, and the inhibition of TLR4-NFκB pathway." (PMID 30519266, 2018). "In fact, the role of TLR4 signaling in intrarenal dendritic cells was documented to contribute to the immunopathology infective pyelonephritis in mice." (PMID 21544241, 2011). "The medullary collecting duct is the first nephron segment exposed to E. coli pyelonephritis during an ascending UTI, and so this result provides proof-of-concept for attenuation of pyelonephritis via pharmacologic interventions that target basolateral TLR4 signaling." (PMID 33239624, 2020). "Therefore, regulation of the TLR4 signaling pathway influences the immune balance and cell death and it is important in clinical trials of pyelonephritis." (PMID 30519266, 2018). "Thus, the influence of dehydration on susceptibility to pyelonephritis is mediated, at least in part, by vasopressin signaling via V2R that impairs uropathogenic Escherichia coli (UPEC)‐UTI clearance by attenuating Tlr‐4‐dependent innate immune responses to UPEC‐UTI." (PMID 33030238, 2020). "During the pyelonephritis, lipopolysaccharide (LPS) coming from uropathogenic Escherichia coli (UPEC) can be identified by TLR4 and induce cytokine production through MyD88-NFκB pathway in renal tubular epithelial cells." (PMID 30519266, 2018).
scleroderma (10 papers, 2012 to 2022). Scleroderma is a rare autoimmune connective tissue disorder characterized by abnormal hardening of the skin and, sometimes, other organs. "In addition, DAMP induced TLR4 activation is known to be a key mediator of myofibroblast differentiation and is relevant in scleroderma as TLR4 and several associated DAMPs are significantly elevated in lesional tissues of SSc patients." (PMID 36726987, 2022). "Extracellular matrix DAMPs that arise during dermal wound healing in patients with scleroderma have also been shown to activate TLR4 and enhance the sensitivity of skin fibroblasts to the fibrogenic effect of transforming growth factor-β1F." (PMID 29422061, 2018). "Moreover, studies in a scleroderma model demonstrate stimulation of B cells with the ECM component hyaluronan activates TLR2 and TLR4 and results in inflammatory cytokine secretion, including IL-6, TNFα, and IFNγ." (PMID 34381449, 2021). "Moreover, CIC activate TLR2, TLR3 and TLR4 in scleroderma, again resulting in two synergistic pairings, TLR2-TLR4 and TLR3-TLR4, that can continue to drive chronic inflammation." (PMID 32629865, 2020).
stable angina (10 papers, 2011 to 2021). "Human studies showed that CD14+ monocyte TLR4 expression is increased in unstable angina and acute MI compared to control and stable angina groups." (PMID 27795867, 2016). "TLR-4 expression levels were higher in patients with ACS than in patients with stable angina." (PMID 25179298, 2016). "In patients with unstable angina, oxLDLs may contribute to monocyte overproduction of some cytokines and above all to that of IL-6 and IL-1β, by upregulating TLR4 expression." (PMID 25757594, 2015). "We investigated the expression level of TLR-4 in ACS, as compared with TLR-2 and patients with stable angina." (PMID 25179298, 2016). "The present study demonstrated while the expression levels of TLR-4 were higher than those of TLR-2 in all patients, those of TLR-4 were higher in patients with ACS than in stable angina." (PMID 25179298, 2016). "The mRNA expression levels of TLR-4 in the plaque debris were significantly higher than those of TLR2 in all enrolled patients, and they were significantly higher in patients with ACS than with stable angina." (PMID 25179298, 2016).
synucleinopathy (10 papers, 2014 to 2025). A neurodegenerative disease that is characterized by the abnormal accumulation of aggregates of alpha-synuclein protein in neurons, nerve fibers or glial cells. "Additional studies in experimental models of PD and α-synucleinopathies demonstrated the important role of TLR4 in α-synucleinopathies and the constitutive expression in microglia and the up-regulation in the substantia nigra." (PMID 34281186, 2021). "For example, in a mouse model of multiple system atrophy, a synucleinopathy, a selective TLR4 agonist promoted microglial clearance of αSyn, while preventing αSyn-mediated TLR4 upregulation of proinflammatory cytokine secretion, resulting in neuroprotection and improved disease outcomes." (PMID 38368939, 2024). "However, there is still controversy in synucleinopathies regarding the advantageous or detrimental functions of TLRs, especially of TLR4." (PMID 37174631, 2023). "Extracellular αSYN can induce inflammatory responses in astrocytes in a TLR4-dependent manner and this may worsen the stress conditions in synucleinopathy brains." (PMID 26346361, 2015). "In in vivo study of transgenic murine model of α-synucleinopathies (ASP), mice overexpressed human α-synuclein (hAS) with TLR4 deficiency (AS/TLR4−/−) exhibited severer neuronal loss, motor disability, and predominant reduced phagocytic activity than those with normal TLR4 expression(AS/TLR4+/+)." (PMID 24395130, 2014). "Interestingly, TLR4 has been shown to be upregulated in microglia in synucleinopathy brains." (PMID 26346361, 2015). "Previous studies have suggested that TLR4 may be involved in synucleinopathies." (PMID 26346361, 2015). "Dysregulation of TLR4, a member of TLR family expressed on cells of the innate immune system including glial cells, plays a crucial role in alpha-synucleinopathies by amplifying glial pro-inflammatory responses triggered by α-Syn aggregates." (PMID 41315232, 2025). "Our data demonstrate the efficacy of a chronic TLR4 stimulation approach in a transgenic mouse model of MSA, a predominantly extraneuronal α-synucleinopathy, characterized by the atypical ectopic aggregation of the protein in oligodendrocytes." (PMID 28676095, 2017).
Ureteral obstruction (10 papers, 2014 to 2025). Obstruction of the flow of urine through the ureter. "has shown CHOP deficiency reduces fibrosis, macrophage infiltration, and TLR4-NFκB signaling in a unilateral ureteral obstruction model of kidney disease." (PMID 28148966, 2017).
vasculitis (10 papers, 2012 to 2025). "CAWS also induced vasculitis in other mouse strains, such as C3H/HeN, C3H/HeJ (TLR4 mutation), DBA/1, A/J, CBA/N, C57Bl, AKR, and BALB/c mice." (PMID 24063402, 2013). "TLR4 has been previously related to GCA since LPS treatment induces vasculitis in human TAs implanted into NOD-SCID mice." (PMID 41225346, 2025). "In that same study, both TLR4 and TLR5 were found to be differentially expressed spatially within the arterial wall, stimulating different types of immune activation and vasculitis when stimulated with either LPS (a TLR4 agonist) or flagellin (a TLR5 agonist)." (PMID 26998496, 2016). "The same authors also showed that TLR4 and TLR5 induce distinct types of vasculitis in GCA patients, with TLR4 ligands causing transmural panarteritis and TLR5 ligands promoting adventitial perivasculitis." (PMID 23690937, 2013). "The importance of TLR4 promoter methylation has previously been demonstrated in vasculitis and various malignancies, but cg05429895 has not previously been studied in the psychiatric context." (PMID 34226490, 2021). "Thus, a lack of GPER1 may prevent the regulation of TLR4 expression and may facilitate the development of vasculitis." (PMID 31474980, 2019).
visceral leishmaniasis (10 papers, 2012 to 2025). A severe form of leishmaniasis characterized by irregular bouts of fever, substantial weight loss, swelling of the spleen and liver, and anemia (which may be serious). "In evolutionary well-established host–parasite systems, such as visceral leishmaniasis (VL) caused by Leishmania spp., TLR4 detects glycosphingophospholipid derived from L. donovani and the proteoglycolipid complex (P8GLC) from L. pifanoi, enhancing the production of proinflammatory cytokines." (PMID 36590595, 2022). "Studies in human disease have shown that patients with visceral leishmaniasis present an increase in TLR4 and TLR9 expression after treatment with miltefosine, generating a strong proinflammatory response which is important in disease resolution." (PMID 29358935, 2017). "The relation of TLR2 and TLR4 in pro- and anti-inflammatory cytokine production was previously investigated in human patients with visceral leishmaniasis (VL)." (PMID 28288677, 2017). "This study supports the immunotherapeutic potential of the PPI as it interacted with TLR4 and promoted macrophage repolarization (M2–M1) to restrict the L. donovani parasite burden and helps in the mounting immune response against experimental visceral leishmaniasis." (PMID 37033485, 2023). "Pharmacological inhibition and immune blot study confirmed the involvement of the PPI in TLR4-mediated phosphorylation of p38 MAPK and dephosphorylation of ERK1/2, repolarizing to pro-inflammatory macrophage state against experimental visceral leishmaniasis." (PMID 37033485, 2023).
Cachexia (9 papers, 2017 to 2026). Severe weight loss, wasting of muscle, loss of appetite, and general debility related to a chronic disease. "Having shown that TLR4 is required for full browning of scAT during cancer-associated cachexia, we subjected WT and TLR4−/− mice to chronic cold (6 °C) challenge to see if TLR4 is required for general adaptive thermogenesis." (PMID 30575787, 2018). "To better understand AT inflammation and the role of macrophage polarization during cancer-associated cachexia, we evaluated AT macrophage (ATMφs) profiles in scAT from WT and TLR4−/− mice during development of the cachexia syndrome." (PMID 30575787, 2018). "Since TLR4 is the major factor in muscle atrophy associated with cachexia, we first determined whether cast immobilization increases TLR4 level in the muscles of mice." (PMID 28432254, 2017). "In line with this, CAC mice displayed markedly elevated serum levels of inflammatory factors, including IL-1, IL-6, TNF-α, TGF-β, IFN-γ, and the cachexia serum marker TLR-4." (PMID 37759730, 2023). "Overexpression of IL-17 has been shown to induce cachexia in mice through Toll-like receptor 4 signaling in muscle tissues." (PMID 36428623, 2022). "Our finding corroborates a recent in vivo study, which demonstrated that the tumours grew slower and the cachexia symptoms were milder in the TLR4-silenced groups." (PMID 36010574, 2022). "In a cancer cachexia animal model, genetic ablation of TLR4 elicited a less severe cachexia with an accompanying lower body weight loss, greater lean body and fat mass, and clinical evidence of reduced wasting compared with the age and weight-matched WT mice." (PMID 30575787, 2018). "Here, we show that both genetic ablation and pharmacological inhibition of TLR4 were able to attenuate the main clinical markers of cachexia in mice bearing Lewis lung carcinoma (LLC)." (PMID 30575787, 2018). "Our study sheds light on TLR4 pathway as a promising target for therapeutic intervention for cachexia." (PMID 30575787, 2018). "At this point, both the genetic ablation and the pharmacological inhibition of TLR4 were able to attenuate both the remodeling of the AT (atrophy and inflammation) and the metabolic dysfunction (lipolysis) induced by cachexia." (PMID 30575787, 2018). "In this scenario, since triglyceride (TG) turnover is affected by cachexia and partially diminished by TLR4 deletion, we evaluated genes involved in fatty acid metabolism in adipocytes." (PMID 30575787, 2018). "We showed in the present study that TLR4 disruption attenuated AT remodeling and metabolic dysfunction during the syndrome, thus suggesting a possible therapeutic target for cancer-induced cachexia." (PMID 30575787, 2018). "As TLR4−/− TB mice were found to be resistant to the lipolytic effects induced by cachexia, we also evaluated some parameters related to the cycle of NEFA release from the breakdown of stored TG and re-esterified to TG (TG turnover)." (PMID 30575787, 2018). "Taken together, we showed in the present study a central role of TLR4 in mediating cancer-induced muscle wasting by activating muscle protein degradation pathways, which opens the door for combating cachexia by targeting a single plasma membrane receptor." (PMID 28536426, 2017). "However, adipocytes from the TLR4−/− mice were less affected by cachexia and showed a very attenuated response to ISO-stimulation." (PMID 30575787, 2018). "Thus, TLR4 signaling mediates muscle atrophy via activation of inflammatory response in cachexia model." (PMID 28432254, 2017). "Interestingly, the TLR4−/− TB animals were shown to be protected against the effects of cachexia, particularly in relation to an absence of weight loss and AT wasting." (PMID 30575787, 2018). "The global knockout, however, did not allow us to track TLR4 function at specific developmental stages of cachexia." (PMID 30575787, 2018). "In general, the effect of cachexia on the expression of scAT metabolic markers was reduced in the absence of TLR4." (PMID 30575787, 2018).
Cachexia (continued). "In general, the effect of cachexia on expression of AT metabolic markers was attenuated in the absence of TLR4, particularly in genes related to glyceroneogenesis and TG reesterification." (PMID 30575787, 2018). "Interestingly, TLR4−/− TB mice showed a significant reduction in AT browning, as well as in the levels of phosphorylation of p38 MAPK, both induced by cachexia." (PMID 30575787, 2018). "Although cachexia induced phosphorylation of p38 MAPK in the WT TB group, there was no change in the TLR4−/− TB group." (PMID 30575787, 2018).
celiac disease (9 papers, 2008 to 2025). An autoimmune genetic disorder with an unknown pattern of inheritance that primarily affects the digestive tract. "Compared with healthy controls, celiac disease patients had increased TLR4 mRNA expression in peripheral blood, while TLR2 and TLR4 mRNA expression was decreased in duodenal biopsy specimens." (PMID 38475833, 2024). "Furthermore, TLRs overexpression has been associated to celiac disease, and accordingly to this observation, the stimulation of PBMCs from celiac patients with pepsin digest of wheat gliadin fraction led to IL-1β secretion via TLR4/MyD88/TRIF/MAPK/NF-kB signaling pathway." (PMID 29795662, 2018). "Recent data indicates that TLR2 and TLR4 expression are upregulated in the intestinal mucosa of treated and untreated celiac sprue patients." (PMID 18365016, 2008). "Increased expression of toll-like receptor 2 (TLR-2) and 4 (TLR-4), claudin 4 (CLD-4), and TNF-α has been shown by different groups in subjects with self-reported gluten intolerance." (PMID 33297984, 2020). "Our results corroborate previously reported results for TLR2 and TLR4 gene expression in IBD and in general for intestinal inflammation such as Celiac Disease and IBS." (PMID 22185629, 2011). "These proteins are resistant to intestinal digestion, can directly activate Toll-like receptor 4 (TLR4) and may support intestinal T cell activation in celiac disease." (PMID 32733456, 2020). "Besides the role of gluten, α-amylase/trypsin inhibitors (ATI) have recently been identified as inducers of an innate immune response via toll-like receptor 4 in celiac disease and non-celiac wheat sensitivity." (PMID 32708800, 2020).
chronic heart failure (9 papers, 2011 to 2026). "In a study, endothelial impairment through TLR4/NF-κB/p38 signaling was shown to play an important role in chronic heart failure." (PMID 31336567, 2019). "TLR4 signaling can exacerbate myocardial injury and adverse remodeling in congestive heart failure." (PMID 39453113, 2024). "Additionally, the presence of congestive heart failure resulted in focal, intense staining of TLR4." (PMID 26998496, 2016). "Indeed, while TLRs expression is enhanced in CF monocytes, fluvastatin dose-dependently inhibits monocyte TLR4 and TLR2 expressions in whole blood from patients with chronic heart failure." (PMID 21826199, 2011).